GPX4 (glutathione peroxidase 4)
Diseases named in the same sentence as GPX4 in open-access papers (continued):
Sharing a sentence is not in itself a finding about the gene and the disease.
tumor (continued). "As a key antioxidant enzyme, GPX4 not only regulates the ferroptosis process but also plays a key role in tumor growth, invasion, and migration." (PMID 40191731, 2025). "The system xc-/GSH/GPX4 axis represents a core antioxidant defense pathway protecting against ferroptosis, and its upregulation often supports tumor cell survival and proliferation." (PMID 40535769, 2025). "The dual‐targeting MIL‐Cu1.8S‐TPP/FA nanoplatform effectively delivered copper ions to mitochondria and iron ions to tumor cells, modulating key ferroptosis‐ and cuproptosis‐related markers, such as GPX4, GSH, FDX‐1, and HSP70." (PMID 40558386, 2025). "Ferroptosis, a mode of cell death discovered relatively recently, occurs frequently during tumor development and s primarily characterized by the inactivation of glutathione peroxidase 4 (GPX4)." (PMID 40788949, 2025). "For example, the new generation FSP1 inhibitor icFSP1 triggers subcellular repositioning and LLPS of FSP1 before ferroptosis and works synergistically with glutathione peroxidase 4 (GPX4) to inhibit tumor growth." (PMID 40231263, 2025). "Complex 3a (biotinylated AuI) effectively inhibits TrxR, leading to the downregulation of GPX4 and initiating the ferroptosis process, thereby sensitizing tumor cells to radiotherapy." (PMID 40709182, 2025). "CMP weakens the antioxidant defense capacity of tumor cells by downregulating the Nrf2/HO-1/xCT/GPX4 signaling pathway, thereby inducing lipid peroxidation and ROS accumulation, and ultimately leading to ferroptosis." (PMID 40539051, 2025). "On the contrary, it has also been suggested that inhibition of HSP90 can forcibly deplete glutathione (GSH) in tumor cells to weaken the antioxidant capacity of the cells, increase ROS content, decrease GPX4 expression, and therefore accelerate ferroptosis." (PMID 40867813, 2025). "Viral and microenvironmental influences add additional layers: EBV-driven GPX4 upregulation, cancer-associated fibroblast (CAF)-derived factors, and immune cell crosstalk all act to suppress ferroptosis and promote tumor survival." (PMID 41373599, 2025). "Increasing evidence indicates that tumor cells can upregulate SLC7A11 and GPX4 to protect cells from radiotherapy-induced ferroptosis, suggesting ferroptosis is crucial to tumor radiosensitivity." (PMID 40084254, 2025). "This research investigates the regulatory mechanisms and properties of GPX4 in various tumor cell types, as well as its molecular structure and biological roles, hoping to propose more effective tumor-targeted therapy alternatives." (PMID 40969276, 2025). "For instance, in osteosarcoma, curcumin induces ferroptosis in tumor cells by regulating the Nrf2/GPX4 signaling pathway." (PMID 40709182, 2025). "This suggests that inhibiting GLS1 can synergize with GPX4 inhibitors (which promote ferroptosis) to effectively suppress tumour growth." (PMID 40259435, 2025). "GPX4, as a pivotal actor in this process, assists tumor cells in mitigating lipid peroxidation, thereby fending off ferroptosis." (PMID 38594779, 2024). "Based on the results of IHC staining, the levels of the cell proliferation markers Ki67 and GPX4 were reduced in BALB/c mouse-derived tumor tissues following BCHE treatment, while transferrin expression was upregulated." (PMID 38906931, 2024). "Second, under the mediation of Nrf-2 and the xCT/GPX4 axis, SA further regulates mitochondrial biogenesis and energy metabolism, impeding tumor cell proliferation and differentiation while revealing upstream inducers of programmed cell death activation." (PMID 39430236, 2024). "The GPX4 inhibitor ML210yne specifically binds to GPX4, resulting in the enrichment of the probe in tumor cells and a higher fluorescence intensity in tumor cells compared to normal cells." (PMID 39451714, 2024). "GPX4 is overexpressed in various cancers, including non-small cell lung cancer (NSCLC), and is associated with tumor invasion, metastasis, and drug resistance." (PMID 39451714, 2024).
tumor (continued). "Since LCN2 inhibits ferroptosis in CRC cells by decreasing intracellular iron levels and stimulating the expression of GPX4 and xCT, elevated levels of LCN2 are associated with tumor progression and drug resistance." (PMID 39359721, 2024). "The use of ferroptosis inducers to inhibit solute carrier family 7 member 11 (SLC7A11) or glutathione peroxidase 4 (GPX4) activity can enhance the sensitivity of tumor cells to radiotherapy (RT)." (PMID 39392831, 2024). "For example, RSL3, a known GPX4 inhibitor, effectively induces ferroptosis in tumour cells by directly binding to and inactivating GPX4." (PMID 39881871, 2024). "Combined with brequinar and sulfasalazine, it synergistically induces ferroptosis and inhibits tumor growth with low GPX4 expression." (PMID 39664391, 2024). "The DHODH inhibitor brequinar selectively inhibits tumor growth with low GPX4 expression by inducing ferroptosis." (PMID 39664391, 2024). "In the TME, anti-tumor immune cells are highly sensitive to ferroptosis, and GPX4 exerts protective effects on T and B cells." (PMID 39600941, 2024). "The use of FSP1 as a pharmacological target in combination with GPX4 inhibitors induces ferroptosis in various tumour types." (PMID 38528461, 2024). "More interestingly, the loss of GPX4 function results in selective ferroptosis in vitro and prevents tumor recurrence in vivo since ‘persister’ cells acquire a dependency on GPX4." (PMID 39721999, 2024). "This mainly causes antitumor T-cell ferroptotic death and dysfunction because T cells with hypoxia-inducible downregulation of GPX4 accumulate lipid peroxides in cell membranes when entering tumor tissues and subsequently undergo ferroptosis." (PMID 39596904, 2024). "Studies have shown that down-regulation of GPX4 can inhibit tumor growth and affect disease progression in OSCC24." (PMID 38987531, 2024). "RSL3 can be used to inhibit GPX4 activity, thereby inhibiting cell viability, clone formation, migration ability, and in vivo tumor growth and promoting cell death." (PMID 37773303, 2024). "TRIM7 induced K48-linked polyubiquitination of SLC7A11 protein, further leading to the inhibition of its downstream GPX4 and acting as a tumor suppressor in GC." (PMID 38509147, 2024). "Bufotalin was reported to improve GPX4 ubiquitination and degradation, increase intracellular lipid ROS and Fe2+ levels, induce the ferroptosis of NSCLCs, and suppress tumor growth in vivo." (PMID 38247539, 2024). "RSL3 and other small-molecule GPX4 inhibitors have been shown to induce ferroptosis in both cultured cancer cells and tumor xenografts in mice." (PMID 38962561, 2024). "Mupirocin significantly decreased the tumor growth, tumor masses, Ki67 expression, GPX4, and SLC7A11 levels, as well as induced the expression of ferroptosis biomarker 4HNE." (PMID 38600610, 2024). "Further research has revealed that KLF2 can bind to the promoter of GPX4 in ccRCC, leading to the downregulation of GPX4 expression, which protects ccRCC cells from ferroptosis, thus promoting tumor cell metastasis." (PMID 39021564, 2024). "Tumor tissues of the CK treatment group showed inhibited GPX4 and SLC7A11 expression and down-regulated p-FOXO1." (PMID 38664638, 2024). "In the xenograft model with high ABCC2 expression, we observed that constricting amino acid intake in conjunction with GPX4 inactivation resulted in notable tumor regression." (PMID 39095325, 2024). "Taken together, these results strongly demonstrated the advantages of AEB effect for generating tumor ferroptosis by GPX4 inhibition, thus contributing to a superior tumor control." (PMID 38212623, 2024). "In order to establish a correlation between PLAG1 and GPX4, IHC analysis was performed on a total of 139 samples of tumor and peritumoral tissues obtained from the HCC patient cohort." (PMID 38745179, 2024). "To determine the role of GPX4 in the CD8+ T cell–mediated antitumor response, we inoculated MC38 tumor cells in control and GPX4 cKO hosts." (PMID 38441967, 2024).
tumor (continued). "In response to this phenomenon, ovarian can directly target GPX4 to disable antioxidant systems with compensatory effects, and significantly inhibited tumour progression." (PMID 38652105, 2024). "Compared to the control and RSL3@LIPO groups, RSL3@LIPO@GEL dramatically suppressed GPX4 synthesis and greatly increased the tumor cell lipid‐ROS levels." (PMID 39308160, 2024). "The results showed that the expression of GPX4 in tumor tissues was significantly higher than that in normal tissues." (PMID 39155888, 2024). "Activation of creatine kinase B (CKB) was identified to phosphorylate GPX4, preventing ferroptosis and fostering tumor growth in mice." (PMID 39036600, 2024). "Genetic ablation of solute carrier family seven member 11 (SLC7A11) or glutathione peroxidase 4 (GPX4) induces ferroptosis in cancer cells, leading to significant tumor suppression." (PMID 39048965, 2024). "Another study targeting GPX4 with circular RNA showed increased levels of ROS and intracellular iron, meanwhile repressing tumor growth in OSCC cells." (PMID 38392321, 2024). "Inhibition of the cystine/GSH/GPX4 pathway induces ferroptosis and suppresses tumor growth with SLC7A11 as a hub of this axis." (PMID 38959043, 2024). "Taken together, these results indicate that CO treatment effectively induce ferroptosis and suppress tumor growth in vivo via decreasing GPX4 expression." (PMID 38263152, 2024). "The transient nature of cilengitide’s effects on GPX4 and mTORC1 activities suggests that its therapeutic window is narrow, necessitating careful consideration of dosing schedules to sustain its anti-tumor effects." (PMID 39590175, 2024). "Emerging evidence implicates that MEF2C silencing repressed GPX4 protein expression in tumor cells under Erastin‐ or RSL3‐stimulated ferroptotic stress." (PMID 39350345, 2024). "The upregulation of the SLC7A11/GSH/GPX4 axis, a key ferroptosis defense system, is a significant evasion mechanism evolved by tumor cells." (PMID 38453898, 2024). "The results above clearly demonstrated that the AEB effect would be beneficial for generating tumor ferroptosis by GPX4 inhibition and ROS generation, resulting in the enhanced anti-tumor capacity." (PMID 38212623, 2024). "Ferroptosis, an iron-dependent programmed cell death first observed in tumor cells in 2012, is triggered by the inactivation of glutathione peroxidase 4 (GPX4)." (PMID 39000568, 2024). "Tumor size, survival time of mice, GPX4 protein levels, 4-HNE levels, and Ki67 expression were measured." (PMID 39368999, 2024). "ORes inhibited tumour growth, enhanced iron deposition, and reduced GPX4 expression in tumour tissues in vivo." (PMID 39881871, 2024). "High RPLP2 expression is linked to unfavorable immune infiltration and positively associates with ferroptosis suppressor GPX4, potentially accelerating ferroptosis to suppress HCC tumor progression." (PMID 39315094, 2024). "In the present research, we identified a novel function of circ_WASF2 in attenuating ferroptosis and tumor growth by regulating miR-634/ GPX4 in PC." (PMID 38704809, 2024). "The gratifying enzymatic activity stemming from the well‐defined Fe‐N/O structure can inhibit tumor proliferation by efficiently downregulating glutathione peroxidase 4 activity and inducing lipid peroxidation." (PMID 38946659, 2024). "BRD4 suppression or inhibitors led to ferroptosis in tumor cells, suppressing GPX4 and System Xc− expression." (PMID 39712490, 2024). "Tumor cell resistance is believed to be dependent on GPX4, so inhibiting GPX4 activity can induce ferroptosis and reverse tumor cell resistance." (PMID 39519171, 2024). "For example, while suppressing tumor growth in a variety of blood and solid tumors, the induction of ferroptosis through GPX4 knockout or iron-feeding can accelerate KRAS-mutant pancreatic ductal adenocarcinoma." (PMID 39188677, 2024).
tumor (continued). "Accordingly, Nrf2/HO‐1/GPX4 was regarded as one of the most concerned anti‐ferroptosis pathways in tumours and non‐cancerous tissues." (PMID 38682349, 2024). "Several reports have demonstrated that tumor cells enhance ferroptosis resistance by increasing GPX4 expression or enhancing enzyme activity." (PMID 38378601, 2024). "Regulatory T (Treg) cells, which usually suppress tumor surveillance, are resistant to ferroptosis due to GPX4 induction." (PMID 38322268, 2024). "It has also been reported that the overexpression of GPX4 decreases the metastatic colonizing capacity of some tumor phenotypes in relation to their ability to produce eicosanoids." (PMID 38539554, 2024). "Benefiting from the enhanced production of ROS and depletion of GSH, NiFe‐LDH‐PEG exhibited a remarkable ability to expedite the accumulation of lipid peroxide (LPO) and deactivate glutathione peroxidase 4 (GPX4), thereby inducing ferroptosis in tumor cells." (PMID 39136080, 2024). "Sulfonamides (SAS) inhibited development of diverse tumor cells through suppressing xCT and inactivating GPX4 to trigger ferroptosis in preclinical models." (PMID 39276361, 2024). "Released SAS inhibited xCT/GPX4, destroying the ‘shield’ that prevented tumor cells from ferroptosis." (PMID 39276361, 2024). "As expected, PPARγ and GPX4 levels were lower in the GW9662-treated tumor tissues than in the control tumors." (PMID 38786003, 2024). "Studies have revealed that GPX4 is highly expressed in metastatic cancers, closely correlating with tumor progression." (PMID 39769177, 2024). "Western blot analysis showed that the protein levels of NRF2 and GPX4 in xenograft tumor tissues were significantly reduced by downregulating PRDX1." (PMID 39430237, 2024). "Treg-specific deletion of GPX4 results in excessive accumulation of lipid peroxides and ferroptosis in Tregs, repressing tumor growth and potentiating anti-tumor immunity concomitantly." (PMID 39614322, 2024). "While RSL3 and ML162 suppress tumor growth and decrease GPX4 expression in 3D spheroid tumor models, ML210 is ineffective in this context." (PMID 39624080, 2024). "GPX4, as a major lipid peroxidation scavenger, has been confirmed to be overexpressed in a variety of tumors, which plays a critical role in protecting tumor cells from ferroptosis." (PMID 38212623, 2024). "For instance, recent studies havCRISPR-Cas9 to silence GPX4 expression in tumor models, resulting in significant ferroptosis-induced tumor regression." (PMID 39871848, 2024). "Research has shown that inhibiting GPX4 not only triggers ferroptosis in tumors but also boosts anti-tumor immunity." (PMID 39867656, 2024). "In vivo experiments and correlation analysis based on clinical specimens further confirmed that TRIM7 inhibited tumor growth through suppressing SLC7A11/GPX4 axis." (PMID 38509147, 2024). "In order to demonstrate the ferroptosis mechanism of Gi-F-CAA for tumor inhibiting, the intracellular GPX4 activity, GSH and Fe2+ ions levels of different treated EJ cells were estimated, respectively." (PMID 38212623, 2024). "In vivo experimental results also demonstrated that BCHE effectively induced ferroptosis through GPX4 downregulation and Transferrin upregulation in tumor-bearing mice." (PMID 38906931, 2024). "A recent study demonstrated ferroptosis landscape of triple-negative breast cancer (TNBC) illustrating the combinatorial effect of anti-PD1 and GPX4 in inducing tumor ferroptosis with augmented anti-tumor immunity." (PMID 38698113, 2024). "Recent studies highlighted that cisplatin can also induce ferroptosis in HCT116 and A549 cancer cell lines by reducing GSH and inactivating GPX4, offering an alternative mechanism for inhibiting tumor growth." (PMID 39595619, 2024).
tumor (continued). "To explore the functional significance of GPX4 in HCC, we analyzed the GPX4 expression in the UALCAN website and found that GPX4 expression was upregulated in tumor tissue samples from HCC patients compared with normal control tissue." (PMID 39519171, 2024). "In conclusion, our newly developed allosteric MIF tautomerase inhibitor MN123 and MIF‐PROTACs can enhance ferroptotic cell death and persistently inhibit tumor cell proliferation in combination with a non‐toxic dose of GPX4 inhibitor RSL3." (PMID 38924362, 2024). "The IHC staining of xenografts tumor tissues showed that the protein levels of NRF2 and GPX4 of xenograft tumor tissues were significantly reduced by PEG-Fe3O4 exposure." (PMID 39483473, 2024). "Resistance to ferroptosis can be an important marker for the growth of tumors and other cancers, which can be stopped with the expression of GPX4, which helps to knock down the metastasis in cancer cell lines 27HC or any other tumor growth." (PMID 39055871, 2024). "In vivo, the volume of tumours in the Har group was decreased, and immunohistochemistry revealed decreased levels of Ki-67 and GPX4 and increased levels of ATG5 and NARL3." (PMID 38499622, 2024). "Consistently, depletion of ACSL4 and GPx4 overexpression has been shown to diminish GBM tumor necrosis and aggressiveness in pre-clinical models of GBM." (PMID 39709480, 2024). "It has been reported that Nrf2 can target and regulate Gpx4, and among the tumor suppressors that regulate ferroptosis, Nrf2 regulates the level of SLC7A11 to control the expression of GPX4." (PMID 38149613, 2024). "Overall, GPX4 overexpression in tumor cells is partly due to the accumulation of H3K4me3 at its gene promoter." (PMID 39595619, 2024). "By depleting intracellular GSH, tumor cells inhibited the GPX4 signaling pathway, promoting ferroptosis to sensitize RT." (PMID 38724978, 2024). "Our findings show that FTO, SLC7A11, and GPX4 protein are also highly expressed in patient tumor tissues than in normal tissues, respectively." (PMID 38600610, 2024). "Immunohistochemical evaluation revealed a mild increase in pro-ferroptotic enzymes like acyl-CoA-synthetase 4 (ACSL4) and a significant, 3-fold decrease in glutathione peroxidase-4 (GPx4) in recurrent GBM tumors relative to the corresponding primary tumor." (PMID 39709480, 2024). "Downregulation of KLF2 has been shown to significantly inhibit ferroptosis and promote tumor cell invasion by weakening transcriptional repression of GPX4." (PMID 38808552, 2024). "Another study showed that XK-81, a metabolite of Leathesia nana (Chordariaceae), decreased SLC7A11 and GPX4 expression and induced ferroptosis in tumor tissues." (PMID 38292937, 2024). "When GPX4 is suppressed, it promotes the accumulation of lipid ROS, accelerates cell death, induces the occurrence of ferroptosis, and inhibits the growth of tumor cells." (PMID 39192972, 2024). "The Western blotting method was applied to detect the expression of PKCiota and GPX4 in tumor tissues, and the GPX4 protein level was lower in PKCiota-silenced tumor tissues." (PMID 38247539, 2024). "GGT1 catalyzes the breakdown of extracellular glutathione into intracellular cysteine, enhancing Gpx4 activity and promoting resistance to tumor cell ferroptosis." (PMID 38965216, 2024). "Tumor ferroptosis mediated by nanomedicines is introduced in the following part according to signal pathways, such as system xc− inhibition, GPX4 inhibition and LPO generation." (PMID 37984863, 2024). "Targeting GPX4- or SLC7A11-induced ferroptosis regulates tumour development and enhances treatment response, offering a promising therapeutic approach for cancers." (PMID 38228715, 2024). "In fact, blocking the main components in the System Xc/GSH/GPX4 antioxidant system has been shown to promote ferroptosis in tumor cells, which can be utilized to treat cancers, particularly drug-resistant tumors." (PMID 38213172, 2024).